IL33 (interleukin 33)
Diseases named in the same sentence as IL33 in open-access papers (continued):
Sharing a sentence is not in itself a finding about the gene and the disease.
tumor (continued). "Harnessing the potential of IL-33/ILC2s axis and understanding the mechanisms underlying their suppressive effect on tumor growth could pave the way for innovative immunotherapeutic approaches." (PMID 38524132, 2024). "Notably, IL-33 is essential for promoting M2-like polarization in macrophages, a process associated with immunosuppressive and tumor-promoting properties." (PMID 40236667, 2024). "Additionally, the necrotic death of tumor cells releases damage-associated molecular patterns (DAMPs) like the high-mobility group box 1 protein (HMGB1) or IL-33." (PMID 38892286, 2024). "Moreover, IL-33 is a key mediator of most ILC2s-associated tumor immunity and ILC2s can even play an opposite role 73-76." (PMID 39309440, 2024). "Dysregulated pathways such as the S100 family, tumor microenvironment and IL-33 signaling that contain MMP12 with high diagnostic ability may have functional relevance in AD’s pathology." (PMID 39338214, 2024). "Furthermore, eosinophils have been implicated in anti-tumor activity through IL-33 and GM-CSF-IRF5 signaling pathways in specific cancer models." (PMID 39518127, 2024). "IL-33, which binds to the IL-1R1 receptor, causes the accumulation of immunosuppressive cells, decreases natural anti-tumor immunity, increases cell proliferation, and stimulates angiogenesis, all of which contribute to tumor progression." (PMID 39456655, 2024). "In addition, IL-33-activated mast cells promote tumor outgrowth by secreting macrophage chemokines to facilitate tumor-associated macrophages (TAMs) recruitment to tumor sites." (PMID 37545500, 2023). "In addition, IL-33 has also been found to be closely associated with tumor progression by regulating tumor cell proliferation, apoptosis, migration, stemness, or chemoresistance in various cancers, including ovarian, colon, and breast cancers 20-22." (PMID 37056569, 2023). "This association may imply that IL-33 and sST2 could have a role in fostering angiogenesis, thereby facilitating tumor growth and progression." (PMID 37762328, 2023). "Furthermore, the absence of mast cells inhibits intestinal-type gastric tumor growth, possibly due to IL-33’s influence on mast cells, hence promoting factors associated with macrophage growth, recruitment, and angiogenesis and supporting tumor growth." (PMID 37686309, 2023). "The cellular composition of the TME, the RNA gene expression profiling of T cells, aberrant chemokine and cytokine expression (i.e., CCL7, IL-33), and mutational tumor burden appear to play an important role in determining the efficacy of check point inhibitors-based immunotherapies." (PMID 37041172, 2023). "Genetic deletion of IL-33 or anti-fungal treatment caused PDAC tumor regression." (PMID 37034706, 2023). "Reversal of IL-33 or anti-fungal treatment caused PDAC tumor regression." (PMID 37910468, 2023). "Furthermore, it has been shown that NK cell depletion in IL-33/ST2-deficient mice is associated with tumor growth promotion." (PMID 35464435, 2022). "Genetic overexpression of IL-33 led to increased tumour burden and expression of Il4, Il5 and Il13 in Th2 cells, and this correlated with increased tumorigenesis in the Apcmin/+ mice, while genetic deficiency of IL-33 reduced overall tumour Il4 and Il13 expression." (PMID 36263033, 2022). "For now, care must be taken before designating Tregs to be responsible for IL-33-mediated CRC (in particular APC-mutation-mediated CRC) in settings where there is a concomitant rise in tumour Treg infiltration and increased cancer burden, in the absence of functional assessments." (PMID 36263033, 2022).
tumor (continued). "High IL-33 expression in tumor tissues has been associated with improved prognosis." (PMID 36291105, 2022). "Continuous IL-33-driven stimulation of Tregs shapes a tumor-promoting immune environment associated with chronic inflammation in the murine skin, and an increase in IL-33 expression and Treg accumulation are observed in the perilesional skin of patients with cancer-prone chronic inflammation." (PMID 35432341, 2022). "In addition, IL-33 has been shown to recruit and induce pro-tumorigenic tumor-associated macrophages." (PMID 35563856, 2022). "In tumor tissues, IL-33 deficiency attenuated Treg immunosuppressive activity against tumor growth." (PMID 35371055, 2022). "For instance, FJ22447 (also known as lncRNA-CAF), which was isolated from OSCC exosomes, has been shown to prevent autophagy-dependent degradation of Interleukin-33 (IL-33), leading to a cancer-associated fibroblast phenotype that enhanced tumor growth and proliferation." (PMID 35008183, 2021). "In search of chromatin-activated neoplasia effectors, the authors observed a rapid increase in alarmin cytokine IL-33 as well as a swift and selective gain of IL-33 locus in KRAS-mutated epithelial cells undergoing injury-facilitated chromatin switch in a BRD4-dependent manner." (PMID 34023857, 2021). "IL-33 directly induced MMP-9 expression in the murine macrophage cell line RAW264.7 that could possibly be linked to tumor invasion and angiogenesis." (PMID 34209038, 2021). "On the contrary, the high expression level of IL-33 in the metastatic samples is associated with prolonged OS and PFS, which may be due to IL-33’s role in the anti-tumor immune responses." (PMID 33621202, 2021). "Moreover, decreased IL-33 expression has been associated with better overall survival and tumor growth inhibition." (PMID 33561993, 2021). "IL-33 promotes M1 to M2 transition of tumor-associated macrophages (TAMs)." (PMID 34895039, 2021). "Despite overall mutational frequencies of the IL33 gene in all tumors examined remain low (0.072–1.391%), some mutations found at the specific motif in each domain of IL-33 may result in aberrant IL-33 function associated with tumor regression or progression." (PMID 34209038, 2021). "The roles of IL-33 in neutrophil-associated tumor immunity are ill-defined." (PMID 34209038, 2021). "IL-33 seems to be involved in the shaping of the immunosuppressive environment during cancerogenesis and high expression of IL-33 in cancer-associated fibroblasts (CAFs) and tumour cells was associated with poor prognosis." (PMID 33602906, 2021). "Interestingly, IL-33 in stromal cells regulated by the pDGF-BB-SOX7 axis promoted HCC metastasis through tumour-associated macrophages." (PMID 33308251, 2020). "Various reviews try to group the IL33-responding immune cell types based on their role in tumor growth, whereby MCs, (tumor associated) macrophages and Tregs are considered pro-tumorigenic, while CD8, NK, NKT, and DC conferring predominantly anti-tumorigenic functions." (PMID 32719677, 2020). "However, transcripts encoding cytokines Cxcl12 and Il33 had a significantly higher expression in the tumor-derived CAFs, suggesting a tumor microenvironment induced activation of these genes in this subpopulation." (PMID 32455670, 2020). "As an attractant, IL-33 can promote the recruitment of Th2-associated cytokines, which act as key mediators for the recruitment of neutrophils, monocytes, NK cells, dendritic cells or T lymphocytes in inflammatory conditions at the site of tumor." (PMID 33005178, 2020). "IL-33 deficient Tregs show attenuated suppressive activity which led to augmented tumor regression." (PMID 32363166, 2020). "In addition, IL-33 recruits signal adapters and kinases to activate transcription factors in tumour cells, which produce the tumour-associated inflammatory microenvironment." (PMID 33308251, 2020). "In addition, loss of nuclear localization abrogates IL-33-induced tumor growth and significantly prolonged survival." (PMID 33020472, 2020).
tumor (continued). "A second study likewise underlines IL-33 expression at the level of the tumor during HCC." (PMID 31507607, 2019). "In the ApcMin/+ mouse model, an IL-33 deficiency reduced tumor burden and decreased mast cell density in the colonic polyps, as well as suppressed the gene expression of mast cell proteases and cytokines that promote angiogenesis, Treg function, and MDSC recruitment within the TME." (PMID 31500217, 2019). "The most recent cytokine to be associated with tumor progression is interleukin (IL)-33." (PMID 30112116, 2018). "In addition, PDGFRβ signalling promotes expression of IL-33 by pericytes, which recruits tumour-associated macrophages that promote tumour metastasis." (PMID 30097696, 2018). "Similarly, patients with multiple myeloma also had diminished plasma levels of IL-33 that were thought to contribute to changes in their immune system that lead to increased tumor growth and loss of immune system control." (PMID 30205617, 2018). "Similarly, in human head and neck SCC, IL-33 has been associated with tumor cell invasion and metastasis." (PMID 30112116, 2018). "Furthermore, loss of IL-33 reduced infiltration of tumor beds by mast cells and regulatory T (Treg) cells, that are both known to be required for polyposis in ApcMin/+ mice." (PMID 30205617, 2018). "IL-33 blockade efficiently inhibited tumor growth of NSCLC xenografts in immune-deficient mice." (PMID 28978138, 2017). "Particularly, the IL-33-triggered signalling in the tumour microenvironment in relation to inflammation-associated tumour invasion is unknown." (PMID 27150562, 2016). "Furthermore, we will explain how IL-33 modulates the tumor-associated inflammatory microenvironment to restrain or promote tumorigenesis." (PMID 28119694, 2016). "Moreover, treatment with recombinant human IL-33 abrogated the TTP-mediated inhibition of tumor growth and metastasis, suggesting that the tumor-suppressive role of TTP in GC is associated with IL-33 suppression." (PMID 27074834, 2016). "Increased IL33 expression in CAFs and in tumor cells is associated with low patient survival." (PMID 28119694, 2016). "To encircle the functional loop between the PDGF-BB-PDGFRβ and IL-33-ST2 signalling pathways in the TAM-associated cancer invasion and metastasis, we took both pharmacological and genetic approaches to execute the IL-33 loss-of-function experiments in PDGF-BB tumours." (PMID 27150562, 2016). "Finally, based on the established role of IL-1 family members in GI-related cancers, the possibility exists that IL-33 can likewise play an important role in GI-associated tumor formation." (PMID 23847622, 2013). "In addition, genetic analyses have linked IL-33-driven type 2 immunity to tumor progression." (PMID 41087719, 2025). "However, when the HIF 1-α expression was correlated with the clinicopathological characteristics on the bases of VEGF and IL-33 expressions the significant association with metastasis disappeared in tumor cells and appeared only with the endothelium of the tumor angiogenesis." (PMID 38313904, 2024). "IL-33 levels are associated with poor prognosis in several cancers due to its contribution to the development of immunosuppressive tumor microenvironment by affecting tumor stromal cells through the activation of carcinoma-associated fibroblasts (CAF) and the induction of VEGF expression." (PMID 37629147, 2023). "This could be relevant in the context of cancer, since tumor-derived IL-33 activates MCs to produce chemotactic molecules that promote tumor-associated macrophages (TAMs)’ infiltration, which, in turn, supports angiogenesis and tumor growth in a mice model of GC." (PMID 35159157, 2022). "Thus, IL-33 appears to promote increases in tumour-associated M2 macrophages in gp130F/F mice." (PMID 35677533, 2022).
tumor (continued). "Interestingly, a current study using humanized mice (NGS mice transplanted with human CD34+ cells and autologous thymus grafts) has demonstrated that co-localization of mast cells and Tregs in IL33+ tumor tissues is significantly associated with resistance to anti-PD1 therapy." (PMID 36211375, 2022). "To this end, we asked whether loss of IL-33 might affect macrophage accumulation at tumour sites." (PMID 35677533, 2022). "However immune cell-associated IL-33 might conversely attenuate tumor progression and provide an option for immunotherapy." (PMID 34298657, 2021). "However, infiltrating ILC2s in tumors express a high level of PD-1, causing reduced anti-tumor effects; this condition could be overcome through the blockade of PD-1 combined with the administration of IL-33, which favors ILC2 activation." (PMID 34680190, 2021). "Furthermore, two recent reports have suggested that the immune cell-associated and proinflammatory cytokine IL-33 might conversely attenuate tumor progression." (PMID 34298657, 2021). "To assess whether tumor-associated mast cells could respond to IL-33, we FACS purified the c-Kit+/FcεR1+ mast cells from the submucosal antrum of WT and gp130FF mice using stomachs from gp130FF; c-KitW-sh/W-sh mice as a specificity control for our purification strategy." (PMID 31227713, 2019). "However, at this stage we can only speculate that subepithelial myofibroblasts and possibly tumor-associated endothelial cells, which have been proposed as sources of IL-1167, may also contribute to epithelial expression of IL-33." (PMID 31227713, 2019). "Additionally, high IL-33 immunoreactivity in metastatic CRC tumor cells has been associated with shorter survival, confirming sST2 as a protective tumorigenesis factor by counteracting protumoral IL-33 effects such as angiogenesis induction and modification of tumor microenvironment." (PMID 31281317, 2019). "Therefore, the IL-33/ST2 axis may participate in the interaction of the tumor microenvironment, mediating processes associated with metastasis in CRC primarily in the left colon." (PMID 31281317, 2019). "Furthermore, the normalized levels of IL-33 in the tumor tissuehomogenates were positively associated with the tumor size of tumor-bearing mice(r = 0.941, P < .05), while the normalized levelsof sST2 were negatively associated with the tumor size (r = −0.786,P < .05; Figure 1Iand J)." (PMID 29950152, 2018). "Furthermore, IL-33 is considered closely associated with IL-18, which has been demonstrated novelly to be upregulated in cancer patients; thus IL-33 may also highlight a close association with tumor." (PMID 27340318, 2016). "Thus, in that study, it is unclear whether IL-33-associated metastasis is owing to large tumour sizes or other mechanisms." (PMID 27150562, 2016). "To examine whether IL-33 is present in 3LL tumour tissues, we first quantified the amount of IL-33 protein in lysates of P29 and A11 tumours established in B6-wild-type (B6) mice and in P29 tumours in IL-33-deficient (IL-33−/−) mice." (PMID 26775708, 2016). "IL-33/ST2 signalling can either promote tumor progression or, in some contexts, enhance anti-tumor immunity." (PMID 42088894, 2026). "Most of these prognostic NRG expressions, except for IL33, were correlated with tumor stage and lymph node metastasis." (PMID 40893939, 2025). "Using genetically modified mice and human tissue samples, we examined how JCAD and IL-33 contribute to tumor-related angiogenesis." (PMID 41374934, 2025). "Since the majority of IL-33 staining was detected outside the tumor core, we performed immunolabeling for IL-33 in U3013 and U3024 cells cultured in vitro to evaluate inherent IL-33 levels in the grafted GBM cells." (PMID 39931535, 2025). "When expressed in tumor cells, IL-33 enhances the immune response and stimulates type 1 antitumor immunity by activating CD8+ T cells and NK cells." (PMID 40149674, 2025).
tumor (continued). "Notably, a recent review article highlighted the direct association between the tumor suppressive effect of exogenous IL-33 and high immunogenic conventional dendritic cells (cDC1s), suggesting that promoting the immunogenicity of DCs with IL-33 may achieve a therapeutic effect." (PMID 39925809, 2025). "In the tumor environment, these factors promote tumor angiogenesis, invasion, metastasis, and immune escape; therefore, targeting macrophages against the IL-33/ST2 pathway also becomes a potential therapeutic strategy." (PMID 39925809, 2025). "Transcriptomic profiling indicates increased IL-33 expression not only in TNBC but also in luminal B tumours." (PMID 41284319, 2025). "We also examined the influence of IL33 overexpression on tumor development in vivo using a subcutaneous xenograft model in nude mice." (PMID 39911848, 2025). "First, we treated APP mice with a neutralizing antibody against IL-33, which eventually reduced the tumor size and number of proliferating cells and ICOS-positive ILC2s within the tumors." (PMID 40761291, 2025). "Taken together, the results of our study suggest that increased levels of IL-33 and IL-4 are responsible for the development of a less favorable type 2 anti-tumor immune response, which contributes to worse therapeutic response." (PMID 40943444, 2025). "IL-33 drives cancer progression through multiple pathways, stimulating and enhancing the growth, survival, and invasion of cancer cells and modulating the tumor microenvironment." (PMID 40647388, 2025). "Specifically, recent studies demonstrate that KLRG1+ ILC2s can acquire anti-tumor functions through IL-10 production and IL-33–mediated activation." (PMID 40497988, 2025). "Consistently, IL-33 reduced tumor growth in colorectal cancer models through the recruitment and the activation eosinophils augmenting their cytotoxicity." (PMID 40050933, 2025). "Through the binding to its specific receptor ST2 expressed by most immune cells, IL-33 can stimulate a variety of immune reactions that can either support or contrast tumor growth." (PMID 40317004, 2025). "IL33, identified as a key prognostic marker, suppresses tumor growth and enhances immune-mediated tumor destruction, underscoring the dual role of efferocytosis in both promoting immunosuppression and revealing therapeutic vulnerabilities." (PMID 40762681, 2025). "The modulation of the IL‐33/ST2L axis by sST2 in the tumor microenvironment clearly impacts tumor growth; however, its effect is likely cell‐type‐specific and context‐dependent." (PMID 40751595, 2025). "IL-33–activated ILC2s not only coordinate with cytotoxic T cells to limit tumor growth, but also promote the formation of tertiary lymphoid structures (TLS) through lymphotoxin (LTα and LTβ) expression." (PMID 40963622, 2025). "IL-33 has also been recognized as a multifunctional cytokine that shapes the tumor microenvironment through its effects on angiogenesis, inflammation, and immune modulation." (PMID 41374934, 2025). "PC cells exposed to fungal components activate this pathway and secrete IL-33, generating an immune tolerance toward the tumor and subsequent progression." (PMID 40641932, 2025). "IL‐33 promoted tumour growth in breast cancer by expanding IL‐13‐producing ILC2s, Tregs and MDSCs, while also reducing NK cell." (PMID 40899118, 2025). "Previous studies have also described an obvious correlation between IL-33 levels and tumor prognosis." (PMID 40943444, 2025). "Blocking IL-33 can induce antitumor immunity in IL-33-positive mice, increasing tumor-specific CD8+ T cell numbers." (PMID 40740858, 2025). "Further validation of IL-33’s role in immune escape and tumour progression is needed using both human PCa samples and relevant animal models." (PMID 40607441, 2025). "Overall, these data suggest that IL-33 in the TME promotes chemoresistance in tumor cells by mediating DDR." (PMID 40216748, 2025).